TRPM4 (transient receptor potential cation channel subfamily M member 4)
Description:
Calcium-activated selective cation channel that mediates membrane depolarization. While it is activated by increase in intracellular Ca(2+), it is impermeable to it. Mediates transport of monovalent cations (Na(+) > K(+) > Cs(+) > Li(+)), leading to depolarize the membrane. It thereby plays a central role in cadiomyocytes, neurons from entorhinal cortex, dorsal root and vomeronasal neurons, endocrine pancreas cells, kidney epithelial cells, cochlea hair cells etc. Participates in T-cell activation by modulating Ca(2+) oscillations after T lymphocyte activation, which is required for NFAT-dependent IL2 production. Involved in myogenic constriction of cerebral arteries. Controls insulin secretion in pancreatic beta-cells. May also be involved in pacemaking or could cause irregular electrical activity under conditions of Ca(2+) overload. Affects T-helper 1 (Th1) and T-helper 2 (Th2) cell motility and cytokine production through differential regulation of calcium signaling and NFATC1 localization. Enhances cell proliferation through up-regulation of the beta-catenin signaling pathway. Plays a role in keratinocyte differentiation. [Isoform 2]: Lacks channel activity.
Synonyms: hTRPM4; LTrpC4; FLJ20041; EKVP6; PFHB1B; TRPM4B
Tractability: Small molecule: a structure with a bound ligand is known; a high-quality ligand is known; it belongs to a druggable protein family. Antibody: UniProt places it where antibodies can reach, with high confidence; its Gene Ontology location is reachable by antibodies, with high confidence; UniProt predicts a signal peptide or a membrane-spanning region; the Human Protein Atlas places it where antibodies can reach. PROTAC: UniProt records ubiquitination sites on it; ubiquitination databases record sites on it; a small molecule that binds it is known.
Target class: Voltage-gated ion channel; Ion channel; Transient receptor potential channel
Gene: Protein-coding gene on chromosome 19 (49,157,741 to 49,211,836, forward strand). Ensembl gene ENSG00000130529.
Subcellular location: Cell membrane (Isoform 1); Endoplasmic reticulum; Golgi apparatus; Cell membrane (Isoform 2)
Subcellular location (Human Protein Atlas): Nucleoplasm; Plasma membrane
Pathways (Reactome):
Sensory Perception: Sensory perception of sweet, bitter, and umami (glutamate) taste
Transport of small molecules: TRP channels
Gene Ontology:
Molecular function: calcium ion binding; calcium-activated cation channel activity; protein binding; sodium channel activity; ATP binding; calcium channel activity; monoatomic ion channel activity
Biological process: calcium-mediated signaling; membrane depolarization during AV node cell action potential; membrane depolarization during bundle of His cell action potential; membrane depolarization during Purkinje myocyte cell action potential; positive regulation of canonical Wnt signaling pathway; positive regulation of cell population proliferation; protein homotetramerization; protein sumoylation; regulation of heart rate by cardiac conduction; regulation of T cell cytokine production; regulation of ventricular cardiac muscle cell action potential; sodium ion import across plasma membrane; transmembrane transport; calcium ion transmembrane transport; dendritic cell chemotaxis; metal ion transport; monoatomic cation transmembrane transport; negative regulation of bone mineralization; negative regulation of osteoblast differentiation; positive regulation of adipose tissue development; positive regulation of atrial cardiac muscle cell action potential; positive regulation of cytosolic calcium ion concentration; positive regulation of fat cell differentiation; positive regulation of heart rate; positive regulation of insulin secretion involved in cellular response to glucose stimulus; and 4 more
Cellular component: endoplasmic reticulum; Golgi apparatus; membrane; plasma membrane; sodium channel complex; neuronal cell body
Genetic constraint (gnomAD): Loss-of-function variants: 124 observed, 132.74 expected, observed/expected ratio (o/e) 0.93, 90% interval 0.81 to 1.08. The upper end of that interval is the gene's LOEUF score, 1.08, which puts it in group 4 of 6, group 1 being the genes least tolerant of losing a copy. Missense variants: 1,658 observed, 1,647.2 expected, observed/expected ratio (o/e) 1.01, 90% interval 0.97 to 1.05. Synonymous variants: 745 observed, 692.34 expected, observed/expected ratio (o/e) 1.08, 90% interval 1.01 to 1.14.
Gene-disease validity (ClinGen):
ClinGen rates the evidence that TRPM4 causes each of these diseases.
Brugada syndrome (autosomal dominant): Refuted. A genetically heterogeneous condition characterized by complete or incomplete right bundle branch block accompanied by ST elevation in leads V1-V3.
Homologues: Orthologues: chimpanzee TRPM4 (99% identical), macaque TRPM4 (96% identical), dog TRPM4 (85% identical), mouse Trpm4 (82% identical), rat Trpm4 (82% identical), pig TRPM4 (80% identical), guinea pig TRPM4 (79% identical), zebrafish trpm4a (46% identical), zebrafish trpm4b.2 (43% identical), zebrafish trpm4b3 (43% identical), Caenorhabditis elegans gon-2 (26% identical), Drosophila melanogaster Trpm (26% identical), and 6 more. Paralogues in human: TRPM5 (42% identical), TRPM2 (36% identical), TRPM3 (30% identical), TRPM1 (30% identical), TRPM8 (29% identical), TRPM7 (28% identical), TRPM6 (27% identical).
Diseases named in the same sentence as TRPM4 in open-access papers:
TRPM4 is named in the same sentence as 183 diseases in open-access papers, as found by Europe PMC text mining. Sharing a sentence is not in itself a finding about the gene and the disease. The quoted sentences say what the papers report.
prostate carcinoma (35 papers, 2014 to 2025). A carcinoma that arises from epithelial cells of the prostate gland. "The over-expression of another TRP channel, TRPM4, which is robustly expressed in prostate cancers, was inversely associated with ERG fusions or the over-expression of ERG and other ETS family transcription factors." (PMID 40332161, 2025). "In prostate cancer, a small study that included 39 patients found an association of higher TRPM4 mRNA expression with higher Gleason scores." (PMID 40332161, 2025). "The two well-expressed channels of the super family, TRPML2 and TRPM4, have divergent associations with the most prevalent prostate cancer molecular aberrations, ERG fusions." (PMID 40332161, 2025). "Two TRP family members with high expression in prostate cancers, TRPML2 and TRPM4, were chosen for further analysis the uncover the associations of their level of expression with clinical and pathologic prostate cancer characteristics." (PMID 40332161, 2025). "In contrast, prostate cancer cases with high TRPM4 mRNA expression were associated with lower ERG fusion frequency than cases with low TRPM4 mRNA expression." (PMID 40332161, 2025). "In several types of cancer, including colorectal tumor and prostate cancer, TRPM4 is overexpressed and contributes to cancer hallmark functions, such as proliferation, migration, invasion, and the epithelial-to-mesenchymal transition." (PMID 36230965, 2022). "Consistent with the study on prostate cancer cells, knockdown of TRPM4 in the cervical cancer-derived cell line HeLa also caused corresponding cell cycle changes, thereby reducing the proliferation of HeLa cells via β-catenin degradation." (PMID 36230965, 2022). "Another study of 210 prostate cancer patient tissues also demonstrated a positive association between TRPM4 protein expression and local/metastatic progression." (PMID 35056097, 2021). "In LnCAP prostate cancer cells, TRPM4-associated Ca2+ influx stimulates AKT1, which in turn increases the inhibitory Ser9 phosphorylation of GSK3β and the total amount of β-catenin." (PMID 33117152, 2020). "(2016) described a positive correlation between the overexpression of TRPM4 in prostate cancer samples and an increased risk of recurrence after radical prostatectomy." (PMID 28614631, 2018). "Increased expression of the TRPM4 channel has been reported to be associated with the progression of prostate cancer." (PMID 28614631, 2018). "In primary endometrial carcinoma cells, high TRPM4 mRNA expression correlated with the epithelial phenotype and less aggressive tumor behavior, consistent with the observed association with lower Gleason score prostate cancers in our study." (PMID 40332161, 2025). "However, further investigations are needed to deepen the knowledge of the molecular mechanism underlying the pro-migratory effect of TRPM4 on prostate cancer cell migration." (PMID 33132914, 2020). "Similarly, no current could be detected upon overexpression of the D984A dominant-negative TRPM4 splice variant in a human prostate cancer cell line (DU145 cells)." (PMID 35056138, 2022). "Several TRP channels were expressed in prostate cancers at the protein level including TRPM4, TRPML1, TRPML2, TRPC1 and TRPP3." (PMID 40332161, 2025). "TRPM4, which was also well expressed in normal prostates, showed moderate to high expression in 75% of prostate cancers." (PMID 40332161, 2025). "Prostate cancer patients with high mean TRPM4 mRNA expression more frequently had low pre-operative PSA values and a lower frequency of ETS family transcription factor positivity (Fisher’s exact test p = 0.02)." (PMID 40332161, 2025). "In prostate cancer, TRPM4 is described as a cancer driver gene in androgen-independent prostate cancer." (PMID 41343534, 2025). "According to microarray-based analysis, miR-150 and TRPM4 (transient receptor potential melastatin 4) have been down and up-regulated in prostate cancer tissue." (PMID 37924077, 2023).
prostate carcinoma (continued). "Current research indicates that TRPM4 promotes the activation of the Wnt/β-catenin and prostate cancer malignancy." (PMID 37924077, 2023). "Different cancers were linked to the expression of different calcium channels, such as TRPM7 in breast cancer and TRPM4 in prostate cancer." (PMID 35816294, 2022). "Increased expression of TRPM4 was found in prostate cancer and prostatic intraepithelial neoplasia tissues, compared to non-malignant tissues." (PMID 36844925, 2022). "TRPM4 also regulates the migration and invasion of prostate cancer (PC-3) cells by altering the expression of genes involved in EMT, including the repression of E-cadherin and upregulation of Snai1, MMP-9, N-cadherin and vimentin." (PMID 36158191, 2022). "The protein expression levels of TRPM4 were reported to be increased in various tumors, such as colorectal cancer, large B cell lymphoma, prostate cancer, and so on." (PMID 35747124, 2022). "For instance, TRPM4 regulates the proliferation, migration, and invasion of prostate cancer cells by altering Ca2+ signalling and thus upregulates β-linked protein oncogene signalling along with its nuclear localisation." (PMID 35493463, 2022). "Higher levels of TRPM4 mRNA were found in prostate cancer upon comparing a pool of 11 normal and 13 precancerous or cancerous prostate tissue-derived data using digital libraries." (PMID 35056097, 2021). "Not only the proliferation of prostate cancer cells, but also their migration/invasion capability, were influenced by TRPM4." (PMID 35056097, 2021). "In one additional study, Christian demonstrated that transient receptor potential melastatin 4 channel (TRPM4) is activated by a rise in intracellular Ca2+ in prostate cancer cells." (PMID 34630112, 2021). "Prostate cancer is, thus far, the most studied type of cancer with regard to TRPM4 expression and function." (PMID 33562811, 2021). "Usually overexpression of TRPM4 was reported in several types of malignancies, such as prostate cancer; breast, cervical, and endometrial cancer; diffuse large B cell lymphoma; and acute myeloid leukemia." (PMID 35056097, 2021). "In prostate cancer (PCa), TRPM4 protein levels were reported to be increased in cancerous prostate tissue compared to benign glands." (PMID 33562811, 2021). "On the contrary, increased TRPM4 mRNA expression was only detected in those prostate cancer samples with a Gleason score higher than 7, which is more likely to spread." (PMID 35056097, 2021). "Further research showed that decreasing TRPM4 expression by shRNA in PC3 prostate cancer cells resulted in decreased migration and invasion capabilities, along with reduced expression of Snail1." (PMID 34360952, 2021). "The authors showed that overexpression of TRPM4 in prostate cancer cell lines increased Snail protein expression and reduced expression of E-cadherin." (PMID 33858332, 2021). "The mechanism of action by which TRPM4 alters the progression of prostate cancer was also described." (PMID 35056097, 2021). "Relatedly, downregulation of TRPM4 by the administration of microRNA-150 also resulted in the inhibition of the EMT in prostate cancer cells." (PMID 34360952, 2021). "In prostate cancer patient samples, it was reported that prostatic intraepithelial neoplasia and prostate cancer tissue present high TRPM4 levels compared to healthy tissue." (PMID 33291725, 2020). "In prostate cancer, TRPM4 staining intensity was significantly higher in prostate cancer cases than benign or non-malignant prostate tissues as well as stromal cells of prostate glands." (PMID 32484822, 2020). "In prostate cancer cells, invalidation of TRPM4 increases GSK3β activity, leading to β-catenin degradation." (PMID 33117152, 2020). "In malignancies, multiple studies have demonstrated the requirement of TRPM4 for the migration and invasion of prostate cancer cells." (PMID 32484822, 2020). "TRPM4 has been found to affect the migratory behaviour of many cell types, including prostate cancer cells." (PMID 33132914, 2020).
prostate carcinoma (continued). "TRPM4 expression induced the proliferation, migration and invasion of prostate cancer cells via TRPM4-mediated activation of β-catenin signaling pathway and epithelial-mesenchymal transition (EMT)." (PMID 32484822, 2020). "Transient receptor potential melastatin‐4 channel (TRPM4) dysregulation contributes to heart conditions, immune diseases, and cervical and prostate cancer." (PMID 31441200, 2019). "Meanwhile, overexpression of TRPM4 promotes cell proliferation by enhancing the β-catenin signaling pathway and epithelial to mesenchymal transition, migration, and invasion in prostate cancer cell lines." (PMID 31105744, 2019). "As c‐Myc and cyclin D1 genes are positive regulators of cell proliferation, we evaluated the effect of TRPM4 knockdown in prostate cancer cell proliferation through MTS and BrdU incorporation assays." (PMID 28614631, 2018). "TRPM4 expression is increased in the transition from prostatic intraepithelial neoplasia (PIN) to prostate cancer." (PMID 28614631, 2018). "Several studies on prostate cancer have suggested that the expression of TRPM4 is a relevant event in the progression of this tumor." (PMID 28614631, 2018). "This current work strongly supports a relationship between TRPM4 levels and β‐catenin stability and function in prostate cancer cell lines." (PMID 28614631, 2018). "This study presents further evidence to show that TRPM4 regulates β‐catenin signaling and enhances the proliferation of prostate cancer cell lines, through a calcium‐dependent regulation of Akt1 and GSK‐3β activity." (PMID 28614631, 2018). "(2015) described the role of TRPM4 in the regulation of store‐operated currents in prostate cancer cell lines and its potential impact on cellular migration." (PMID 28614631, 2018). "The role of TRPM5 channels has been shown in lung cancer, TRPM1 in melanoma, and TRPM4 channel in prostate cancer as well." (PMID 29875336, 2018). "The STIM and the Orai proteins are putative targets for cancer therapy, and TRPM4 was more recently identified as a potential target for prostate cancer therapy." (PMID 29951353, 2017). "Patients with higher expression levels of TRPM4 in prostate cancer glands compared to matched benign glands have an increased risk of biochemical recurrence [104•]." (PMID 29951353, 2017). "This article summarizes what is known about the dysregulation of the key molecular players involved in SOCE (STIM1, STIM2, Orai1, Orai2, and Orai3) and the negative regulator TRPM4 in prostate cancer." (PMID 29951353, 2017). "We compared TRPM4 activity in hPEC, as well as in the prostate cancer cell lines LNCaP, DU145 and PC3." (PMID 26496025, 2015). "We thus evaluated TRPM4 antibody staining in paraffin-embedded human prostate cancer tissues from 20 patients." (PMID 26496025, 2015). "We investigated TRPM4 protein expression in cancer tissue samples from 20 patients with prostate cancer." (PMID 26496025, 2015). "Down-regulation of TRPM4 strongly decreased cell migration of DU145 and PC3 cells, suggesting a role for TRPM4 in prostate cancer invasion—the initial step for tumor metastasis." (PMID 26496025, 2015). "Whereas in hPEC TRPM4 exhibited currents of 70 ± 13 pA/pF, in the prostate cancer cell lines, the TRPM4 current size was 35 ± 12 pA/pF in LNCaP, 59 ± 17 pA/pF in DU145, 9 ± 5 pA/pF in PC3 cells for 10 μM Ca2+ and 56 ± 11 pA/pF in PC3 cells for 25 μM Ca2+." (PMID 26496025, 2015). "TRPM4 contributes to the migration of prostate cancer cells and is thus an interesting potential pharmacological target." (PMID 26496025, 2015). "To further delineate the role of TRPM4 in prostate cancer, we investigated the potential of TRPM4 to limit Ca2+ signals in the prostate cancer cell lines DU145 and PC3." (PMID 26496025, 2015). "A recent publication by Schinke and colleagues demonstrated elevated levels of TRPM4 in androgen-insensitive prostate cancer cells and suggested a role for TRPM4 as a cancer driver gene." (PMID 26496025, 2015).